INO80B-WBP1 (INO80B-WBP1 readthrough (NMD candidate))
Gene: Protein-coding gene on chromosome 2 (74,455,088 to 74,460,884, forward strand). Ensembl gene ENSG00000274049.
Genetic constraint (gnomAD): Missense variants: 474 observed, 446.03 expected, observed/expected ratio (o/e) 1.06, 90% interval 0.99 to 1.15. Synonymous variants: 238 observed, 178.65 expected, observed/expected ratio (o/e) 1.33, 90% interval 1.2 to 1.48.